TGFBR2 (transforming growth factor beta receptor 2)
Diseases named in the same sentence as TGFBR2 in open-access papers (continued):
Sharing a sentence is not in itself a finding about the gene and the disease.
pancreatic cancer (44 papers, 2002 to 2025). "In fact, some studies have shown that conditional loss of SMAD4 or TGFBR2 in Pdx1-Cre/LSL-KRas mice develop advanced aggressive pancreatic cancer." (PMID 29156578, 2017). "Research on targeted therapies for FLT4 and TGFBR2 mutations remains limited in pancreatic cancer." (PMID 40994638, 2025). "On the other hand, common TGFBR2 variants, especially V216I and T340M in the East Asian population, have been reported to be potential biomarkers in aortic aneurysmal diseases and pancreatic neoplasms." (PMID 37029342, 2023). "We notice that for 1 patient with pancreatic cancer and tissue biopsy, for instance, there is one nonsense mutation in TGFBR2 with a current unknown knowledge status." (PMID 32196460, 2020). "Intracellular miR-665 transfection led to the decreased expression of TGFBR1 and TGFBR2, suppressing the proliferation and invasion of human pancreatic cancer cells." (PMID 39838364, 2025). "In colorectal and pancreatic cancers, the TGF-β signalling pathway is frequently abolished by mutations in SMAD4 or TGFBR2 (Massagué, 2008; Levy and Hill, 2006)." (PMID 37439249, 2023). "Another study showed that suppression of BRD4 by JQ1 robustly blocked TGFBR2 level in pancreatic cancer cells." (PMID 37737256, 2023). "Taken together, these results suggest that circSEC24A can promote the expression of TGFBR2 through miRNA sponge effect, thereby enhancing the tumorigenicity of pancreatic cancer." (PMID 34906151, 2021). "The overexpression of LINC00462 improved TGFBR1 and TGFBR2 expression levels to activate the SMAD2/3 signaling pathway in pancreatic cancer." (PMID 33622186, 2021). "Further study confirmed that circSEC24A alleviated suppression on target TGFBR2 expression by directly sponging miR-606 and then influenced the tumorigenesis of pancreatic cancer." (PMID 34906151, 2021). "In pancreatic cancer cells, the deletion of an SE in TGFBR2 significantly downregulated the expression of TGFBR2, resulting in impairment of the migration and EMT induced by TGF-β66." (PMID 32382065, 2020). "Several studies have shown that TGFBR2 inhibits cell growth, invasion, migration, and metastasis in breast and pancreatic cancer." (PMID 32046777, 2020). "Since TGFBR2 has been proved to be a target of miR-665 in pancreatic cancer and other cancer cells, we only focued on the novel target, NR4A3, of miR-665 in BC." (PMID 31209222, 2019). "Similar to a 10-bp polyadenine tract within the TGFβ receptor type II gene (TGFBR2) that is prone to frameshift mutations in gastrointestinal cancers, mutations in ACVR2 have been identified in colorectal and pancreatic cancers." (PMID 26447543, 2015). "A recent pathway-based analysis of pooled GWAS data reported that T-helper (Th) immune response genes (Th1/Th2), such as transforming growth factor-beta receptor 2 (TGFBR2), chemokine ligand 18 (CCL18), and IL13RA2, were associated with pancreatic cancer risk." (PMID 25945796, 2015). "USP33 is also reported to enhance the protein stability of transforming growth factor beta receptor 2 (TGFBR2) by removing the K63-linked ubiquitin chains on TGFBR2, thereby enhancing transforming growth factor-beta (TGF-beta) signaling and promoting pancreatic cancer cell migration and invasion." (PMID 40695806, 2025). "Moreover, Previous study has reported TGFBR2 inhibitor as a potent drug for pancreatic cancer treatment, the TGFBR2 inhibitor, Galunisertib significantly improved overall survival in patients with unresectable pancreatic cancer." (PMID 34906151, 2021). "Our study revealed that circSEC24A could regulate the progression of pancreatic cancer in a TGFBR2-dependent way." (PMID 34906151, 2021). "Therefore, circSEC24A/miR-606/TGFBR2 signaling axis might be one of the indispensable factors affecting the therapeutic effect of pancreatic cancer." (PMID 34906151, 2021).
pancreatic cancer (continued). "However, only miR-103 was directly involved in the regulation of pancreatic cancer-associated processes: E-cadherin signalling events (CDH1), TGF beta signalling pathway (TGFBR2, APC, CDH1, CREBBP, EP300, SMAD3, TSC2), and altered TFG-beta SMAD dependent signalling (TGFBR2, SMAD3, and FBXW7)." (PMID 29285254, 2017). "DKO cell lines formed pancreatic tumors in mice, but their histological features were distinct from SMAD4 or TGFBR2 single knockouts as they produced mixed epithelial/mesenchymal morphologies with cells expressing both E-cadherin and vimentin." (PMID 38573819, 2024). "(C) Summary of pancreatic tumor development in nude mice by KPC cells of the indicated STAT3, SMAD4, and TGFBR2 genotypes presented." (PMID 38573819, 2024). "(A) Representative H&E staining of pancreatic tumor sections derived from KPC cells of the indicated genotypes, SMAD4 KO (n=12), SMAD4/STAT3 DKO (n=3) and TGFBR2/STAT3 DKO (n=3), where n denotes the number of mice injected." (PMID 38573819, 2024). "By engineering anti-mesothelin CAR-T cells with CRISPR/Cas9 to knockout the TGFBR2, a complete tumor remission was achieved after intratumor or intravenous injection of edited CAR-T cells in the pancreatic tumor PDX mice." (PMID 36139356, 2022). "Our data demonstrates that circSEC24A competitively binds to miR-606, in turn regulates expression of TGFBR2, activating AKT signaling to promote cell proliferation, migration and invasion of pancreatic cancer." (PMID 34906151, 2021). "We demonstrate that IPMNs and MCNs are precursors of invasive pancreatic cancer, that alterations in ATM, GLI3, and SF3B1 are present in these lesions, and that SMAD4/TGFBR2 alterations are likely drivers of invasion in a subset of cases." (PMID 32796935, 2020). "Here, the authors present the evolutionary analysis of neoplastic cysts and report them as precursors of invasive pancreatic cancer, and that SMAD4/TGFBR2 alterations are likely drivers of invasion in a subset of cases." (PMID 32796935, 2020). "Meanwhile, the down-regulated transforming growth factor beta receptor II (TGFBR2) and CCND1 were significantly enriched in both the pathways of chronic myeloid leukemia (p = 9.85E−03) and pancreatic cancer (p = 4.69E−02)." (PMID 27716259, 2016). "When RNA from pancreatic tumors was used, antisense intronic transcription was detected in three additional loci (ATF2, TGFBR2 and MAP3K1), which produced both sense and antisense messages." (PMID 22078386, 2011). "With such a work frame in place, researchers have shown that an impairment of the tumor growth factor beta receptor II (TGFBR2) is yet another approach to preventing CAR-T cell exhaustion in the tumor stroma and to gain a long-term effect in pancreatic cancer patient-derived xenografts (PDX)." (PMID 36139356, 2022). "Pancreatic tumors were detected within 3 weeks following implantation of 104 parental control, STAT3 knockout (KO), SMAD4 KO, or TGFBR2 KO PDAC cells, and there was no statistical difference in tumor latency between the groups." (PMID 38573819, 2024).
colon carcinoma (41 papers, 2006 to 2025). "For example, left-half colon cancer has high expression of epiregulin (EREG) and amphiregulin (AREG) proteins, while right-half colon cancer has high mutation rates of the TGFbR2 and BRAF genes." (PMID 41182556, 2025). "Inactivating mutations in TGFBR2 are frequently present in tumours that exhibit microsatellite instability, such as those found in subsets of colon carcinomas, which express truncated mutant forms of TGFβR2." (PMID 36267157, 2022). "Proximal colon tumors showed higher mutation frequencies than distal tumors on TGFBR2 (30.0% vs 2.8%, P < 0.001), ATM (20.0% vs 2.8%, P = 0.020), BLM (25.0% vs 2.8%, P = 0.005), and PTEN (15.0% vs 1.4%, P = 0.032) genes." (PMID 31548566, 2019). "In primary colon cancer tumors, we observed that nuclear p21 localization correlated with TGFBR2 expression while loss of nuclear p21 is associated with ACVR2A expression, respectively." (PMID 26497569, 2015). "From a clinical perspective, our findings are consistent with recent work showing that induction of EMT is impaired in microsatellite instable (MSI) colon cancer cells due to the presence of TGFBR2 mutations." (PMID 24658684, 2014). "We previously observed greater than 50% overlap between ACVR2 and TGFBR2 mutations in primary MSI colon tumors, possibly because of additive effects in mediating the growth response, which are currently under investigation." (PMID 20011542, 2009). "The TGFBR2 gene is mutated in several cancer types with ∼90% of colon cancers characterized by MMR deficiency displaying frameshift mutations in a polyadenine tract of TGFBR2, which encodes the signal peptide of the expressed protein." (PMID 19401691, 2009). "The effect of TGFBR2 loss in colon cancer formation was investigated in a conditional knockout Cre-Tgfbr2(flx/flx) mouse model, in which genetic ablation of the Tgfbr2 gene led to increased proliferation due to the inability to inactivate Cdk4 expression and kinase activity." (PMID 34439114, 2021). "Similarly, TGFBR2 mutations are particularly common in MSI colon cancers, which generally have an improved prognosis." (PMID 27270652, 2017). "While TGFBR2 is mutated in numerous human cancers with particular prevalence in mismatch repair-deficient colon cancer, its functional relevance in gastric cancer is unknown." (PMID 25315765, 2014). "Here, we used the TGFBR2-deficient MSI colon carcinoma cell line HCT116 as a model system." (PMID 23468914, 2013). "The timing of ACVR2 mutations in MSI colon cancer may be similar to that of TGFBR2 in which the frameshift mutations occur in high grade dysplasia at the interface to malignancy." (PMID 20011542, 2009). "Conversely, all MSS colon cancer specimens with activin signaling component loss expressed TGFBR2." (PMID 20011542, 2009). "Also, we found a subset of MSS colon cancers that lost ACVR2 expression, akin to TGFBR2 loss found in MSS colon cancers." (PMID 20011542, 2009). "Microsatellite stable (MSS) colon cancers have intact DNA mismatch repair, but may harbor TGFBR2 kinase domain mutations." (PMID 20011542, 2009). "For instance, TGFBR2 mutational frequency is higher in MSI-H colon carcinomas (70 to 90%) than in MSI-H endometrium carcinoma (17 to 19%), suggesting that biological features and functional roles of target genes may differ depending on the tissue of tumor origin." (PMID 20979647, 2010). "Indeed, a mutated form of TGFBR2 can be observed in up to 80% of colon cancer patients with HNPCC." (PMID 20490264, 2010). "We previously generated intestinal tumor-derived organoid cells (AKTP+/M cells) from compound mutant mice, in which genetic alterations were simultaneously introduced to four colon cancer driver genes: Apc, Kras, Tgfbr2, and Trp5326." (PMID 32393735, 2020). "But we found that TGFβ signaling associated genes TGFBR2 and TGFBI was highly expressed in MSS subtype of colon cancer, suggesting the potential inhibition of TGFβ signaling pathway in MSI subtype colon cancer patients." (PMID 31221124, 2019).
colon carcinoma (continued). "We also observed the upregulation of Bmp2 and Tgfbr2 by MOB1A/B knockdown in the Caco-2 colon cancer cell line." (PMID 30349003, 2018). "TGFBR2 and ACVR2A are commonly mutated in microsatellite unstable (MSI) colon cancers, which is the second most common genomic subtype." (PMID 26497569, 2015). "Both TGFBR2 and ACVR2A harbor coding microsatellites and mutations in MSI colon cancers which are associated with loss of protein expression." (PMID 26497569, 2015). "The ACVR2/TGFBR2/SMAD4 wild type microsatellite stable colon cancer cell line FET and ACVR2/TGFBR2 wild type/SMAD4-null SW480 colon cancer cells were treated with either activin or TGFβ and cellular growth was assessed." (PMID 22761777, 2012). "Both ligand specific pathways are commonly inactivated in MSI-H colon cancers, for which we previously observed greater than 50% overlap between ACVR2 and TGFBR2 mutations." (PMID 22761777, 2012). "Mononucleotide tracts in the coding regions of the TGFBR2 and BAX genes are commonly mutated in microsatellite instability-high (MSI-high) colon cancers." (PMID 21949851, 2011). "TGFBR2 and MSH3 mutations were detected more frequently in right MSI-H colon carcinomas (P = 0.00005 and P = 0.0000005, respectively) than in MSI-H rectal and sigmoid carcinomas." (PMID 20979647, 2010). "Reduced ALK-5 and TGFBR2 expression correlates with a shorter survival rate of colon cancer patients, as does reduced expression of the coreceptor betaglycan in breast and prostate cancer patients." (PMID 20490264, 2010). "Colon cancer cell models highlight the relationship between defective DNA MMR and TGFBR2 and ACVR2 frameshift mutations." (PMID 18941508, 2008). "In our data, TGFBR2 was also served as a protective prognostic factor for stage II A colon cancer." (PMID 27008710, 2016). "Colon cancers with high frequency microsatellite instability (MSI-H) are associated with mutations in several genes with coding repetitive sequences, such as transforming growth factor β receptor 2 (TGFBR2) and activin type 2 receptor (ACVR2)." (PMID 20011542, 2009). "TGFBR2 gene is mutated in colon cancer (20%) but shows no mutation in rectal cancer." (PMID 32580435, 2020). "However, unlike in other cancer types such as colon cancer, genetic mutations of its component genes, such as TGFBR2 and SMAD2/4, are rare." (PMID 30181549, 2019). "Using ACVR2A/TGFBR2 wild type FET colon cancer cells, FET with SMAD4 knockdown, and the SMAD4-null colon cancer cell line SW480, we found a SMAD4-independent increase in pAkt Ser473 after activin treatment compared to control and TGFβ treatment." (PMID 26497569, 2015). "Humoral responses to mutant TGFBR2 protein have been identified by ELISA, but only in a minority (10%) of MSI-High colon cancer patients." (PMID 21209843, 2010). "A significant subset of colon tumors displayed a decrease in phosphorylated SMAD with intact ACVR2 and TGFBR2, indicating a separate primary event downstream of the primary receptors." (PMID 20011542, 2009). "In colon cancer, members of the miR-17–92 cluster activate Wnt/β-catenin signaling and epithelial-mesenchymal transition, while suppressing TGF-β signaling via direct targeting of TGFBR2, VEGFA and HIF1A." (PMID 41473312, 2025). "In the syngeneic murine colon carcinoma (MC38) model, although primary tumor growth in Tgfbr2-cKO mice was slower than that in WT mice, local IR resulted in a more pronounced inhibition of tumor growth in Tgfbr2-cKO mice." (PMID 38099498, 2023). "For instance, TGFβ signaling associated genes TGFBR2 and TGFBI were both not enhanced in MSI colon cancer patients’ tissue and MSI colon cancer cell lines." (PMID 31221124, 2019). "However, in colon cancer patients, β-catenin (CTNNB1) and TGFBR2 were all unfavorable effects on tumor progress." (PMID 31221124, 2019). "We have previously observed that loss of nuclear p21 expression correlates with either presence of ACVR2A or absence of TGFBR2 in primary colon cancers." (PMID 26497569, 2015).
colon carcinoma (continued). "In contrast, neither ligand was growth suppressive in the absence of SMAD4 in ACVR2/TGFBR2 wild type/SMAD4-null SW480 colon cancer cells or following SMAD4 knockdown in SMAD4 wild type FET cells." (PMID 22761777, 2012). "Here, we report a substantial number of primary colon cancers with loss of nuclear p21, which correlates with presence of ACVR2 and absence of TGFBR2." (PMID 22761777, 2012). "The levels of TGFBR2 were shown to regulate the downstream signaling pathway: high expression induces the Smad-dependent signaling pathway while a low expression triggers signaling via the non-Smad-dependent MAP/ERK pathway in colon cancer." (PMID 30863498, 2019).
lung carcinoma (39 papers, 2005 to 2025). "Our results show that TAL1 is a lung-specific gene associated with lung carcinoma and directly regulates TGFBR2, which was previously annotated as a tumor suppressor gene." (PMID 36902378, 2023). "The member of TGFb receptor family - TGFBR2 is a tumor suppressor in lung cancer, and the loss of TGFBR2 expression is associated with worse prognosis of both squamous cell cancer and adenocarcinoma." (PMID 37006265, 2023). "The combined functional and molecular level evidence suggests I50V mutation on TGFBR2 as a potential biomarker for lung cancer." (PMID 28740175, 2017). "Tgfbr2 deficiency boosted the inhibitory effects of TGFβ on the TME in lung cancer." (PMID 36504444, 2023). "Accordingly, TGFBR2 mutation predicts lung cancer resistance to checkpoint inhibitors." (PMID 37006265, 2023). "We have characterised the protein interaction of TGFBR2 associated with potential colorectal and lung cancer comorbidity, explaining how the mutation of Ile 73 to Val (residue 50 in the PDB structure) can cause the loss of the interaction and this, in turn, distorts the function." (PMID 28740175, 2017). "Clinically, low-expressed TGFBR2 in lung cancer tissues is related to poorer prognosis, particularly at an early cancer stage." (PMID 39525474, 2024). "To further verify the function of TGFBR2, we designed two siRNAs targeting TGFBR2 in this study and aimed to induce a quiescent or dormant state of the TGFBR2 gene in lung cancer cells." (PMID 39364312, 2024). "Collectively, our data solidly showed that MYOCD recruited PRMT5/MEP50 methyltransferase complex and epigenetically modified TGFBR2 promoter region to silence its transcription in lung cancer cells." (PMID 33995678, 2021). "Taken together, our data showed that MYOCD inhibited lung cancer cell stemness through inhibiting TGFBR2 transcription." (PMID 33995678, 2021). "Ectopic expression of PRMT5 or MEP50 in A549 lung cancer cells dose-dependently inhibited TGFBR2 promoter reporter activity." (PMID 33995678, 2021). "Our above data suggested that MYOCD inactivation led to TGFBR2 hyperactivation and enhanced stemness of lung cancer cell." (PMID 33995678, 2021). "The method was applied to the A549 lung cancer cell line, and we identified specific kinases known to have an important role in this type of cancer (TGFBR2, EGFR, PHKG1 and CDK4)." (PMID 24961498, 2014). "However, cancer studies showed that EZH2 regulated TGFBR2 via the H3K27me3-dependent mechanism, by which hypoxia and YAP/TAZ signal attenuated TGFBR2 expression in prostate and lung cancer, respectively." (PMID 37710230, 2023). "Hence, TGFBR2 status should also be evaluated as a potential biomarker for responses to immunotherapy in PDAC, an associated that is now supported in lung cancer patients." (PMID 35155243, 2022). "Interestingly, the data have shown several fold upregulation of DNA repair genes like RAD51b, RAD 18 and SOX2 cancer stem cell markers, MUC5AC and TGFBR2 in radiation resistant and caveolin-1, overexpressed A549 lung cancer cells." (PMID 34762666, 2021). "There may be a similar molecular mechanism of TGFBR2 loss to reprogram TME in NPC and lung cancer." (PMID 39049720, 2024). "These GO terms encompass six genes relevant to lung cancer found primarily in “Pathways in cancer” GO and partially overlapping with two other GOs: FLT3, FOXO1, CSF1R, RUNX1, PPARG, and TGFBR2." (PMID 39201328, 2024). "We then set out to treat K+/M- lung cancer with combination of inhibitors for MEK1/2, TGFBR2, and CSC stemness." (PMID 33995678, 2021). "TGF-β2 signals through TGFBR1, TGFBR2, SMAD2, and SMAD4 to upregulate WNT7B mRNA expression in lung cancer cells." (PMID 30971692, 2019). "SCUBE3 was reported to modulate cancer progression by binding to TGFBR2 and activating TGFB signaling in human lung cancer cells." (PMID 30093865, 2018).